BDNF (brain derived neurotrophic factor)
Diseases named in the same sentence as BDNF in open-access papers (continued):
Sharing a sentence is not in itself a finding about the gene and the disease.
schizophrenia (continued). "Meanwhile, there is also evidence of lower BDNF levels in prefrontal cortex and in CSF of subjects diagnosed with schizophrenia." (PMID 28358316, 2017). "Reduced serum brain-derived neurotrophic factor (BDNF) level had also been reported in patients with catatonic schizophrenia as compared to patients with other subtypes of schizophrenia." (PMID 28114315, 2017). "The pathogenesis of schizophrenia is not fully understood; however, a decrease in BDNF expression and the resultant hypoactivity in N-methyl-D-aspartate (NMDA) receptor have been implicated in the pathology of Schizophrenia." (PMID 29246029, 2017). "In summary, these observations and studies need careful analysis in order to assign a role to BDNF in the molecular pathology of schizophrenia." (PMID 28387726, 2017). "In this study, we aimed to investigate the relationship between serum BDNF levels and schizophrenia considering metabolic profiles and gender differences in patients with schizophrenia." (PMID 28562580, 2017). "In schizophrenia patients, a decreased level of plasma BDNF has been noted, although findings from different studies have been inconsistent." (PMID 29246029, 2017). "Multiple studies have assessed the effects of antipsychotic treatments on BDNF expression in preclinical models, as well as of BDNF serum levels in treated schizophrenia patients." (PMID 29321734, 2017). "Even though there is much evidence in different resources proving that levels of BDNF vary in the brains of patients with schizophrenia, the results are debatable." (PMID 29287075, 2017). "MMP-9 influences synaptic plasticity, thought to be relevant to the neurobiology of schizophrenia possibly by converting pro-brain-derived neurotrophic factor (BDNF) to BDNF." (PMID 28588507, 2017). "BDNF is a regulator of microglial-mediated synaptic plasticity, suggesting a greater reduction in neuroplasticity with advancing age in schizophrenia." (PMID 29201010, 2017). "Low serum BDNF protein levels were determined in drug-naïve patients with schizophrenia, but also in schizophrenic patients who were treated with different antipsychotics." (PMID 28358316, 2017). "Overall, the possibility that the microbiota affects BDNF expression and contributes to the development of schizophrenia warrants further investigation." (PMID 29246029, 2017). "Further studies are needed to further clarify the role of gender in BDNF levels in patients with schizophrenia." (PMID 28562580, 2017). "Decreased BDNF levels in patients with schizophrenia were recently confirmed in a metaanalysis that was comprised 41 studies and more than 7000 participants." (PMID 29287075, 2017). "The results reveal that although BDNF levels play an important role in schizophrenia, how much and in what ways this role changes during the drug-naïve duration remains a subject in need of more research." (PMID 29287075, 2017). "A recent meta-analysis demonstrated that peripheral levels of serum and plasma BDNF were moderately decreased in schizophrenia compared with controls." (PMID 27783051, 2016). "For example, a meta-analysis identified the evidence of a positive correlation between lowered levels of peripheral BDNF in schizophrenia and increasing age." (PMID 27783051, 2016). "A reduction in peripheral BDNF levels has been reported in patients with schizophrenia compared to healthy controls, including medication naïve and first-episode schizophrenia patients." (PMID 27783051, 2016). "By means of bisulfite pyrosequencing, Igekame and colleagues found a significant increase (about 1 %) of the methylation level of one CpG site in the promoter I of BDNF in schizophrenia patients compared with controls." (PMID 27267954, 2016). "The results of our review show that, while the efficacy of each NPI on serum or plasma BDNF levels in patients with schizophrenia was inconsistent, NPIs have a beneficial effect on peripheral BDNF in schizophrenia." (PMID 27783051, 2016).
schizophrenia (continued). "A recent meta-analysis showed that the plasma/serum brain-derived neurotrophic factor (BDNF) levels in schizophrenia patients were significantly lower than those in controls." (PMID 26770258, 2016). "We also reported that treatment with olanzapine for 4 weeks significantly increased plasma BDNF levels in acute schizophrenia patients." (PMID 26770258, 2016). "Another neurotrophin which has also been found to be reduced in schizophrenia is brain-derived neurotrophic factor." (PMID 27992436, 2016). "We conducted a systematic review and meta-analysis to review the efficacy of NPIs on peripheral serum and plasma BDNF in subjects with schizophrenia (including schizoaffective disorder)." (PMID 27783051, 2016). "In one of the brain open-access databases, we revealed a significant but minor (1.3 %) difference in the average methylation level of BDNF promoter IV in schizophrenia patients." (PMID 27267954, 2016). "A truncated TrkB lacking its kinase domain, which acts as a dominant-negative receptor for BDNF and prevents TrkB/BDNF signalling, has been reported to be increased in schizophrenia patients." (PMID 26839058, 2016). "For example, post-mortem studies have revealed that both mRNA and protein levels of BDNF and TrkB are decreased in multiple cortical areas in schizophrenia patients." (PMID 26839058, 2016). "They compared patients with schizophrenia to healthy controls in terms of their decision making ability and serum BDNF levels." (PMID 27147997, 2016). "According to the methylation data, the relative expression level of BDNF was significantly higher in schizophrenia patients than in controls." (PMID 27267954, 2016). "In subgroup analyses, we demonstrated significant effects of non-exercise interventions, including diet products and cognitive training, on blood BDNF levels in schizophrenia." (PMID 27783051, 2016). "With respect to these non-exercise interventions, few studies have reported the relationship between these types of interventions and BDNF levels in schizophrenia." (PMID 27783051, 2016). "Given the overlapping pathophysiology of dysregulation in BDNF, glutamate and gamma-Aminobutyric acid (GABA) shared by Fragile X and schizophrenia, the potential for common causal pathways seems plausible." (PMID 27895608, 2016). "PCP caused acute changes in brain derived neurotrophic factor (BDNF) and NMDAR1, akin to prefrontal changes seen in schizophrenia patients and some rodent models for the disorder." (PMID 27382048, 2016). "Conversely, we found that plasma BDNF levels were significantly increased in our cohort ofpeople with schizophrenia compared to healthy adults." (PMID 25162472, 2015). "This appears to be the case in schizophrenia, where a more accentuated decrease in BDNF is present with longer untreated psychosis." (PMID 26621529, 2015). "Future studies to determine the mechanism ofthe abnormal BDNF and brain activity relationship in schizophrenia would provide furtherinsight into the role of trophic factors in schizophrenia." (PMID 25162472, 2015). "Differences in TrkB and BDNF mRNA in schizophrenia patient/matched control pairs correlated positively with differences in GAD67 mRNA." (PMID 25762898, 2015). "This preliminary study is thefirst to describe a relationship between plasma BDNF levels and neural activity duringlearning in healthy adults, which is disrupted in schizophrenia." (PMID 25162472, 2015). "Conversely, we obtained an effect that wasopposite to what would be predicted, such that patients with schizophrenia (who weresignificantly older than the controls) displayed significantly higher BDNF levels thancontrols." (PMID 25162472, 2015). "Astrocytes also express the BDNF receptors, TrkB and p75, and schizophrenia is closely related to imbalanced circuit-level expression of BDNF signaling molecules." (PMID 26700309, 2015). "Altered BDNF signaling has been demonstrated in several regions of the schizophrenia brain by post mortem studies." (PMID 26700309, 2015).
schizophrenia (continued). "Huang and Lee (2006) measured BDNF levels in a group of 126 patients with schizophrenia, 11 of which had a history of suicide attempts." (PMID 26718989, 2015). "BDNF signaling is thought to play an important role in the pathophysiology of schizophrenia, but the contribution of BDNF signaling by hippocampal astrocytes is currently unclear." (PMID 26700309, 2015). "Several studies have shown a reduction of BDNF mRNA,protein and BDNF trkB receptor in schizophrenia." (PMID 25162472, 2015). "One reason that general predictions about blood–brain relationships in schizophrenia aredifficult to make is that studies of peripheral BDNF levels in schizophrenia have reportedinconsistent results." (PMID 25162472, 2015). "BDNF mRNA levels were also significantly decreased in layer V of STG in schizophrenia and in layer VI of STG in schizophrenia, BPD and MDD." (PMID 24802307, 2014). "Reduced BDNF levels were observed in medicated and drug naive schizophrenia patients as indicated by meta-analysis with unexplained population heterogeneity." (PMID 25025909, 2014). "We show a significant reduction in the expression of BDNF mRNA, particularly in deeper cortical layers and predominantly in schizophrenia in most cortical areas examined (except in the OFC)." (PMID 24802307, 2014). "Brain-derived neurotrophic factor is also well known for its involvement in the pathophysiology of neuropsychiatric disorders including schizophrenia." (PMID 25414641, 2014). "Together with the already increased BDNF baseline expression found in epilepsy, a comorbid psychotic state would display milder symptoms than in schizophrenia, as it is indeed depicted in interictal psychosis." (PMID 25027171, 2014). "Specific genetic risk factors seem to dispose patients with schizophrenia to develop OCS and risk-conferring polymorphisms has been defined in SLC1A1, BDNF, DLGAP3, and GRIN2B and in interactions between these individual genes." (PMID 26556409, 2014). "Secondly, as mentioned, BDNF regulates other neurotransmitters putatively involved in the aetiology of schizophrenia, including glutamate, GABA, and serotonin." (PMID 24672724, 2014). "These decreases in trkB–TK+ combined with the significant decreases described in various layers for BDNF would indicate that BDNF/trkB signaling is likely to be compromised across multiple cortical areas in schizophrenia." (PMID 24802307, 2014). "The relatively lower methylation and higher expression of BDNF was also observed in schizophrenia patients compared to healthy controls." (PMID 24382160, 2014). "Taken together, these results suggest that, whereas multiple cortical layers can contribute to the overall reduction in DLPFC BDNF mRNA, the reductions in the deeper layers, where BDNF expression is highest, has the largest decrease in schizophrenia." (PMID 24802307, 2014). "The levels of brain-derived neurotrophic factor (BDNF) are significantly decreased in patients with schizophrenia and correlate with impairments in cognitive function." (PMID 25538582, 2014). "We compared patients with schizophrenia to healthy controls with respect to their decision-making ability and serum BDNF levels." (PMID 25538582, 2014). "Taken together with our findings, these results suggest that quetiapine has a direct neurotrophic effect in schizophrenia, promoting neuroplasticity via the up-regulation of BDNF." (PMID 24672724, 2014). "A recent meta-analysis of studies showed that blood levels of BDNF are reduced in both medicated and drug-naïve patients with schizophrenia." (PMID 25414641, 2014). "Fourth, the schizophrenia patient group was receiving antipsychotics, a relevant problem because of the influence of the drugs on the BDNF levels." (PMID 25538582, 2014). "A recent meta-analysis revealed that the serum BDNF levels in schizophrenia patients are lower than those in healthy individuals." (PMID 25538582, 2014).
schizophrenia (continued). "Bonferroni testing showed that BDNF mRNA levels were significantly reduced in both schizophrenia (P=0.001; 33% reduction) and MDD (P=0.03; 24% reduction) compared with controls." (PMID 24802307, 2014). "Recent research has provided evidence for the contribution of BDNF to the pathophysiology of schizophrenia." (PMID 25538582, 2014). "A meta-analysis of studies conducted in patients with schizophrenia has identified a consistent, moderate decrease in blood BDNF levels compared to healthy controls." (PMID 25548672, 2014). "For example, it has been shown that chronic patients with schizophrenia on clozapine had marginally significant higher BDNF levels compared to patients on FGAs." (PMID 24551075, 2014). "In the present longitudinal study we investigated the alterations of hippocampal volume and serum BDNF levels in a sample of first episode patients with schizophrenia before the initiation and following a short term exposure to SGAs." (PMID 24551075, 2014). "Our study observations add further support to the role for BDNF in schizophrenia pathogenesis and suggest a potential novel link between deficient BDNF and FRS." (PMID 23847552, 2013). "As a group, schizophrenia patients (28.8 ± 11.7 ng/mL) had significantly lower serum BDNF than healthy controls (34.9 ± 8.2 ng/mL) after controlling for the potential confounding effects of age and sex (F = 7.8; p = 0.006)." (PMID 23847552, 2013). "For example, post-mortem studies have found significant reductions of BDNF gene expression and protein levels in the brains of people with schizophrenia." (PMID 24155701, 2013). "Post-mortem studies have reported decreased levels of BDNF protein in the hippocampus and prefrontal cortex in brains of schizophrenia patients." (PMID 23847552, 2013). "miR-26b has also been shown to regulate the expression of brain-derived neurotrophic factor (BDNF), a gene strongly implicated in neurodevelopment and related disorders (i.e., schizophrenia), including the effects of PAE." (PMID 23915435, 2013). "Although the exact nature of Nrg1xE and their consequences for schizophrenia have to be evaluated further, an involvement of the GABAergic, glutamatergic and BDNF systems seems likely." (PMID 23966917, 2013). "In this study, we evaluated serum BDNF in antipsychotic-naïve schizophrenia patients (N = 59) in comparison with healthy controls (N = 60)." (PMID 23847552, 2013). "To ascertain this relationship further, in this study, we have evaluated antipsychotic-naïve schizophrenia patients in comparison with healthy controls for serum BDNF; also, we concurrently assessed the Schneiderian FRS in patients." (PMID 23847552, 2013). "In this study, 59 co-morbidity free, antipsychotic-naïve schizophrenia patients were compared with 60 healthy controls for serum BDNF levels." (PMID 23847552, 2013). "In summary, our study observations add further support to the role for BDNF in schizophrenia pathogenesis." (PMID 23847552, 2013). "A valid approach for studying the role of BDNF in schizophrenia patients is the measurement of plasma or serum levels." (PMID 23785335, 2013). "As a group, schizophrenia patients (28.8 ± 11.7 ng/mL) had significantly lower serum BDNF than healthy controls (34.9 ± 8.2 ng/mL) after controlling for the potential confounding effects of age and sex (F = 7.8; df = 117; p = 0.006)." (PMID 23847552, 2013). "Given the increasing emphasis on the role of neurotrophic factors in the neurodevelopmental pathogenesis of schizophrenia, BDNF has attracted significant attention in schizophrenia research studies." (PMID 23847552, 2013). "The deficient BDNF level seems to be predominantly contributed by schizophrenia patients with FRS; to the best of our knowledge, this is the first time report of relationship between FRS and deficient BDNF in schizophrenia." (PMID 23847552, 2013).
schizophrenia (continued). "This is similar to the reduction of BDNF protein observed in schizophrenia, therefore these animals can be used as a model to examine the role of BDNF in behaviors related to schizophrenia." (PMID 23781174, 2013). "Reports of BDNF plasma levels in patients with chronic schizophrenia in comparison to control subjects have been somewhat inconsistent." (PMID 23785335, 2013). "This needs to be evaluated further with concurrent analyses involving genotype as well as peripheral level of BDNF along with brain imaging studies in the same cohort of schizophrenia patients." (PMID 23847552, 2013). "Diazepam was reported to reduce levels of BDNF in animals, and, more recently, decreased levels of serum BDNF have been observed in schizophrenia patients with catatonia treated with lorazepam." (PMID 24024214, 2013). "The relation between peripheral and brain BDNF has been demonstrated by a recent study that showed parallel changes in BDNF levels in plasma and CSF in patients with schizophrenia, indicating that plasma BDNF levels reflect the brain changes in BDNF levels." (PMID 23785335, 2013). "A 2007 meta-analysis of case-control studies found a relationship between BDNF Val66Met SNP and substance-related disorders, eating disorders, and schizophrenia." (PMID 23785335, 2013). "Post-mortem studies have consistently shown reduced BDNF expression in the hippocampus and dorso-lateral prefrontal cortex (DLPFC) of patients with schizophrenia, two brain regions that are highly implicated in the pathophysiology of the disorder." (PMID 23781174, 2013). "Reduced brain-derived neurotrophic factor (BDNF) signaling has been shown in the frontal cortex and hippocampus in schizophrenia." (PMID 24155701, 2013). "The brain derived neurotrophic factor (BDNF) was recently proposed as a third candidate gene, because the Val66Met polymorphism was found to be associated with OCS in schizophrenia." (PMID 23950745, 2013). "At the molecular level, numerous mRNA transcripts and proteins are altered in both schizophrenia and bipolar disorder, including brain-derived neurotrophic factor (BDNF), glutamic acid decarboxylase-67 (GAD-67) and growth-associated protein-43 (GAP-43)." (PMID 22427805, 2012). "EGR3 is also a target gene for Brain-derived neurotrophic factor (BDNF) and Neuregulin 1 (NRG1), both of which are schizophrenia susceptibility genes." (PMID 22276163, 2012). "Catechol-o-methyl transferase (COMT), brain-derived neurotrophic factor (BDNF), and neuregulin 1 (NRG1) have all been implicated in the pathophysiology of schizophrenia and bipolar disorder (BD)." (PMID 24278715, 2012). "Other studies addressed the schizophrenia-relevant role of BDNF (brain-derived neurotrophic factor)." (PMID 23150836, 2012). "Induction of EGR3 by BDNF enables EGR3 to control the expression of Gamma-aminobutyric acid receptor (GABAR), which is also a candidate risk gene for the schizophrenia." (PMID 22276163, 2012). "The network also includes some well-studied schizophrenia candidate genes (e.g., BDNF, DRD2, GRIN1 and GAD1)." (PMID 20156358, 2010). "For schizophrenia, BDNF, Rantes and EGF gave the strongest signals, with p-values ranging approximately between 10−30 and 10−60." (PMID 20161799, 2010). "It has also been reported that miRNA hsa-miR-195 regulates BDNF and alters the expression of downstream GABAergic transcripts in schizophrenia." (PMID 20156358, 2010). "For instance, age effects do not appear to modify substantially the highly significant associations found for BDNF, RANTES, EGF, TIMP-1, ENA-78 and MDC levels with schizophrenia." (PMID 20161799, 2010). "For BDNF, previous studies in schizophrenia have produced mixed results, with evidence of increased, decreased, or no change in serum or plasma BDNF level." (PMID 20161799, 2010).